MET (MET proto-oncogene, receptor tyrosine kinase)
Diseases named in the same sentence as MET in open-access papers (continued):
Sharing a sentence is not in itself a finding about the gene and the disease.
acute myeloid leukemia (13 papers, 2014 to 2025). Acute myeloid leukemia (AML) is a group of neoplasms arising from precursor cells committed to the myeloid cell-line differentiation. "Tivantinib is reported as a more prominent GSK3α and GSK3β inhibitor and a weak MET inhibitor in acute myeloid leukemia." (PMID 39458991, 2024). "It has been reported that combined FGFR1 and MET inhibition can improve treatment efficacy in vitro and in xenografts of acute myeloid leukemia models." (PMID 31963871, 2020).
medullary thyroid cancer (13 papers, 2011 to 2022). "MET protein is rarely observed in other thyroid tumours, including follicular carcinoma, anaplastic carcinoma, and medullary carcinoma." (PMID 26062519, 2016). "In 2012, FDA approved cabozantinib, an inhibitor that targets VEGF, MET, and other tyrosine kinase pathways for the treatment of metastatic medullary thyroid cancer." (PMID 25294187, 2015). "Cabozantinib, an inhibitor targeting VEGF, MET, and the “anexelekto” receptor tyrosine kinase, was approved by FDA in 2012 to treat metastatic medullary thyroid cancer." (PMID 34804015, 2021). "Cabozantinib (XL184), targeting VEGFR1/2, MET, RET, KIT and FLT3, has been assessed in several cell line models and has been approved by the FDA for the treatment of progressive medullary thyroid cancer." (PMID 31040922, 2019). "Cabozantinib is another FDA-approved tyrosine kinase inhibitor targeting three important pathways: MET, vascular endothelial growth factor (VEGF), and rearranged during transfection (RET) for the treatment of metastatic medullary thyroid cancer." (PMID 27703281, 2016). "Moreover, several strategies to impair SF/HGF-MET aberrant activation are currently under investigation in numerous clinical trials, and cabozantinib (MET, RET, and VEGFR2 multikinase inhibitor) received FDA approval for the treatment of medullary thyroid carcinoma." (PMID 28532501, 2017).
diffuse large B-cell lymphoma (12 papers, 2008 to 2025). "Indeed, c-MET has been shown to be overexpressed in 26.0%–73.2% of cases of diffuse large B-cell lymphoma, and to be significantly associated with intracellular signaling pathways." (PMID 38089883, 2023). "c-MET is frequently overexpressed in diffuse large B cell lymphoma (DLBCL), occasionally present in Burkitt or in follicular lymphomas (BL, FL) but negative in mantle cell (MCL) or marginal zone lymphoma." (PMID 30642077, 2019). "Moreover data from these reports, on the supposed relationship between enhanced c-MET expression and disease pathogenesis, are sometimes conflicting, especially in diffuse large B cell lymphoma (DLBCL) or in Hodgkin disease (HD)." (PMID 30642077, 2019). "And by inhibiting the activation of the MET/PI3K/AKT pathway, the proliferation ability of diffuse large B-cell lymphoma cells was inhibited and their apoptosis was promoted." (PMID 36502446, 2022). "Geniposide also significantly inhibited diffuse large B-cell lymphoma (DLBCL) cell proliferation and promoted apoptosis; this effect was at least partially mediated through the HCP5/miR-27b-3p/MET axis." (PMID 35630796, 2022). "Similarly, in diffuse large B cell lymphoma (DLBCL), patients demonstrated increased HGF and c-MET in their blood, bone marrow, plasma, and pleural fluid, which correlates with clinic outcomes." (PMID 40520181, 2025).
endometriosis (12 papers, 2008 to 2025). The growth of functional endometrial tissue in anatomic sites outside the uterine body. "MET was the target gene of our study, and further studies are required to understand its role in the pathogenesis of endometriosis." (PMID 40405976, 2025). "Recent research suggest that many putative driver genes and aberrant pathways including ARID1A mutations, PIK3CA mutations, MET activation, HNF-1β activation, and miRNAs dysfunction, play crucial roles in the malignant transformation of endometriosis to OCCC." (PMID 34659566, 2021). "The ARID1A, PI3K/AKT/mTOR, MET, and HNF-1β pathways are frequently activated and are considered promising targets for the treatment of endometriosis-associated OCCC." (PMID 34659566, 2021). "We have reported a variety of molecular events such as ARID1A mutations, PIK3CA mutations, MET activation, HNF-1β activation, and miRNA dysfunction in endometriosis-associated OCCC." (PMID 34659566, 2021). "Therefore, therapies that disrupt HGF/c-MET signaling could be considered for further investigation in endometriosis patients, with the aim of retarding or halting disease progression." (PMID 40076450, 2025). "Importantly, we demonstrated that O-ASC CM-induced cell migration could be curtailed in endometriosis with c-MET inhibition." (PMID 40076450, 2025). "Moreover, atypical endometriosis and EAOC may share several molecular alterations such as ARID1A and PIK3CA mutations, PTEN loss, MET amplifications, and HNF1B overexpression, suggesting a common molecular mechanism for malignant development." (PMID 27992377, 2017). "Using machine learning algorithms, five key genes were selected in the endometriosis: BST2, IL4R, INHBA, PTGER2, and MET." (PMID 40405976, 2025). "The epithelium of the endometriosis lesion expresses high levels of IGF-1R and c-MET, the receptor for IGF1/2 and HGF, respectively." (PMID 35740424, 2022). "Furthermore, in cases of endometriosis and adjacent OCCC components, the incidence of MET overexpression is gradually increasing." (PMID 34659566, 2021). "Thus, c-MET-expressing tissues, including the FTE and the endometriosis lesions, all receive the signal and may exhibit growth and invasion phenotypes." (PMID 35740424, 2022).
metastatic carcinoma (12 papers, 2012 to 2025). A carcinoma which has spread from the original site of growth to another anatomic site. "Since increased expression of MET and phosphorylation in cancer cells was confirmed, the data suggested that the metastatic cancer cells mainly bind with HGF, which is released into the pericancerous liver microenvironment in a paracrine manner." (PMID 40076928, 2025). "Thereby, demonstrating that MET targeting is a viable future therapeutic option in the treatment of metastatic cancer." (PMID 22736953, 2012). "In combination, the inhibition of MET-mediated pSTMN1S16 and AR activity could significantly advance the treatment of metastatic cancers." (PMID 40723207, 2025). "Our results proved that HGF/MET axis plays a crucial role in directing cell-autonomous functions regulating cancer cell dissemination, supporting a possible use of MET inhibitors in metastatic cancers." (PMID 37345079, 2023). "Our data showed that the prevalence of MET expression in CTCs isolated by CellSearch® is greater than previously reported data (20% MET-positive scores of 2+ or 3+), and even higher to the expected MET expression in patients with metastatic cancer." (PMID 32102486, 2020).
prostate tumor (12 papers, 2010 to 2024). "In agreement with our findings, treatment of both PC3 and LNCaP prostate tumor cells with a MET inhibitor resulted in reduced cell proliferation." (PMID 37668356, 2023). "In total 25 cases revealed tumour expansion into extra-prostatic fat tissue; in 10 extra-prostatic tumour areas (40.0%) high c-MET expressing cells were encountered." (PMID 22110593, 2011). "Moreover, we detected higher phosphorylation levels of MET and AKT in primary human prostate tumors with higher compared with lower FOXP2 protein abundance." (PMID 37668356, 2023).
astrocytoma (11 papers, 2015 to 2025). "Increased mRNA levels of MET, the gene encoding HGFR, has been described in both canine astrocytomas and oligodendrogliomas." (PMID 37368789, 2023). "These cell lines express MET transcript and protein at levels comparable to the E98 astrocytoma cell line, which is very well-characterized by our group and was used as a positive control." (PMID 30881919, 2019). "Others have reported that faster progressing mutant IDH1-driven astrocytomas had increased copy numbers in EGFR, MYC, MET, and CDK6 compared to slower-progressing patients." (PMID 40188944, 2025). "Many studies on MYBL2, E2F7, CCN4, and MET genes promote tumor progression by promoting tumor proliferation, differentiation, and migration, which may also contribute to the malignant progression of IDH-mutant astrocytoma." (PMID 41460424, 2025).
hereditary papillary renal cell carcinoma (11 papers, 2005 to 2025). A familial carcinoma inherited in an autosomal dominant trait. "Apart from being crucial in mammalian development and epithelial morphogenesis, MET is overexpressed in several human cancers and germline mutations of the MET gene have been reported in hereditary papillary renal carcinoma." (PMID 15785735, 2005). "The first activating mutations of MET were identified in hereditary papillary renal carcinoma (HPRC), and the authors suggested that the mutations affecting the kinase domain of MET (M1149T, V1206L, V1238I, D1246N, and Y1248C) were causal in HPRC." (PMID 37760640, 2023). "SPORADIC:Activating mutations or amplifications of MET proto-oncogene in >80% of sporadic cases.Gains in chromosomes 3, 7, and 17.FAMILIAL:Hereditary papillary renal carcinoma (HPRC)." (PMID 36428491, 2022). "In hereditary papillary renal carcinoma, an oncogene, mesenchymal-epithelial transition factor (MET), has been revealed to be mutated, although the incidence of c-MET mutations is low in sporadic papillary RCC." (PMID 24348776, 2014). "Missense mutations in MET tyrosine kinase domains were recently detected in hereditary papillary renal cell carcinoma (RCC), childhood HCC and other cancers, and these residues were speculated to inhibit MET enzymatic activity." (PMID 27013592, 2016).
invasive breast carcinoma (11 papers, 2012 to 2025). A carcinoma that infiltrates the breast parenchyma. "Amplification of the MET gene (located on chromosome 7), like mutation, is unusual in invasive breast cancer: in a study of 155 patients, Carracedo and colleagues did not identify MET amplification at all (although 22% of tumours showed low-grade polysomy)." (PMID 25887320, 2015). "Previous studies have linked HGF/MET signaling with poor outcome in invasive breast cancers." (PMID 24025166, 2013). "While MET expression was significantly suppressed in primary tumor tissues in breast invasive carcinoma (BRCA) and upregulated in kidney chromophobe (KIHC), HOTAIR expression was significantly higher and lower, respectively." (PMID 32650779, 2020).
lung squamous cell carcinoma (11 papers, 2008 to 2024). "Another report showed that a patient with squamous cell lung cancer, harboring c-MET amplification, had partially responded to crizotinib." (PMID 24885608, 2014). "Indeed, we have shown here that an inverse correlation exists between TIAM1 and HUWE1 (and TIAM1 and c-MET) in squamous cell lung carcinoma." (PMID 25543140, 2015). "Compared to the small cell or squamous cell lung cancer patients, more LUAD patients could benefit from the target therapies including but not limited to EGFR TKIs, VEGFR inhibitors, or c‐MET inhibitors." (PMID 39431755, 2024).
malignant glioma (11 papers, 2008 to 2022). A grade III or grade IV glioma arising from the central nervous system. "High levels of LRIG3 is associated with the downregulation of EGFR and MET signaling in malignant gliomas, supporting the idea that LRIG3 may be a novel target for anti-angiogenic therapy." (PMID 33718179, 2021). "Thus, the U87M2, U118, and SF295 malignant glioma cells were determined to be models sensitive to MET inhibition, while DBM2 and U251M2 cells were used as insensitive models for further analysis." (PMID 26381735, 2015). "Furthermore, targeting gene fusions involving EGFR, FGFR, MET or NTRK may soon represent a promising therapeutic option for several types of cancer including malignant glioma." (PMID 35372034, 2022). "With respect to radiation-induced EMT, it has been repeatedly shown that treating malignant glioma cells with sub-lethal doses of radiation in vitro significantly enhances tumor cell motility through upregulation of TGF-β, HGF/c-MET, and vascular endothelial growth factor (VEGF) signaling." (PMID 28821904, 2018). "Specifically in the context of malignant glioma, these include NOTCH1, NOTCH2, MET, and CDK6." (PMID 22479456, 2012).
bone metastasis (10 papers, 2014 to 2025). Transfer of a neoplasm from its primary site to bones. "We also investigated the potential associations between MET alterations and the location of metastatic sites and showed a significant correlation with lymph nodes and bone metastasis (both P < 0.02)." (PMID 29866143, 2018). "In PC, an increase in c-MET expression was observed and appeared to be associated with progression of bone metastasis." (PMID 25277255, 2014). "While clinical trials have provided proof-of-principle that blocking MET activity reduces bone metastasis and pain levels in mCRPC, decreasing the side effects and adverse pharmacokinetics of drug interactions remain a major challenge." (PMID 40723207, 2025). "MET phosphorylation was particularly evident in subcutaneous (5/5, 100%) and bone metastasis (6/8, 75%) samples." (PMID 40299443, 2025). "In our previous study, higher expression of MET and matriptase was observed in bone metastasis compared with nephrectomy specimens by immunohistochemistry." (PMID 29890660, 2018). "Furthermore, the overall postoperative survival rate was significantly higher in the MET negative group than in the MET positive group, which indicates that MET and matriptase affect not only the formation of bone metastasis, but also patient survival." (PMID 29890660, 2018).
gallbladder cancer (10 papers, 2020 to 2024). "Unsatisfactory results derived from the use of MET inhibitors such as cabozantinib (abnormal MET activation has been found in 12%–58% of iCCAs) PI3K/AKT/mTOR inhibitors showed exiguous responses despite 12.5% of gallbladder cancers displaying activated mutations of PIK3CA." (PMID 32423017, 2020). "Furthermore, genetic variations associated with inflammation, apoptosis, DNA repair, drug metabolism, hedgehog signaling, Wnt signaling, TGF-β, MET-related pathways, or aberrant levels of associated proteins have demonstrated significant associations with gallbladder cancer." (PMID 39210450, 2024). "In gallbladder cancer and several other tumor tissues, the expression of MET, a tyrosine kinase, is markedly up-regulated." (PMID 39210450, 2024). "Inhibitors targeting MET have demonstrated significant effectiveness in inhibiting proliferation, migration, and invasion of gallbladder cancer cells." (PMID 39210450, 2024). "The subclone of undifferentiated components contained FGF19 and MET amplifications that is not found in the tubular component and is reported to be associated with poor prognosis in liver and gallbladder carcinomas." (PMID 32487254, 2020). "We have explored and validated the anti-tumor activity of Bufalin by inhibiting c-MET mediated MEK/ERK and PI3K/AKT signaling pathways in gallbladder cancer." (PMID 32231716, 2020).
liver disease (10 papers, 2007 to 2025). "In conclusion, our results identified the basal phosphorylation of MET as key node integrating alterations in hepatocytes and suggest it as an informative metric for liver disease burden and patient recovery after liver surgery." (PMID 38216754, 2024). "One study in mice, though, found that the deletion of MET led to the development of NASH, supporting a possible role of MET in the development of liver disease." (PMID 40489530, 2025).
Obesity (10 papers, 2014 to 2025). Accumulation of substantial excess body fat. "Remarkably, excess hepatic PAI-1 in the context of obesity-induced T2DM disrupts HGF activation in the liver, leading to impaired signaling through its receptor that is encoded by the gene MET." (PMID 39825925, 2025).
diabetes (9 papers, 2018 to 2026). "Diabetes prevalence varied from 11.5% among patients treated with ALK inhibitors (26 patients) to 26.7% among patients treated with MET inhibitors (8 patients)." (PMID 41196597, 2025). "A pancreas-specific knockout of the MET gene in mice accelerates the onset of diabetes." (PMID 30237882, 2018).
gastrointestinal stromal tumor (9 papers, 2007 to 2022). "Moreover, RAS pathway activation has been shown to predict primary resistance to imatinib in gastrointestinal stromal tumors and to confer secondary resistance to MET inhibitors in MET-addicted cells." (PMID 25691052, 2015). "Furthermore we evaluated the gene expression of KIT as well as the alternative RTK FLT3, CSF1-R, PDGFRB, AXL and MET in mutated and non-mutated gastrointestinal stromal tumors by qPCR using the identified reference genes." (PMID 21171987, 2010).
malignant mesothelioma (9 papers, 2010 to 2022). A malignant neoplasm of the pleura or peritoneum, arising from mesothelial cells. "In malignant mesothelioma (MPM), the localization of c-mesenchymal-epithelial transition (c-MET) on plasma membrane indicated longer survival of patients." (PMID 35127947, 2022).
oral cancer (9 papers, 2015 to 2025). "In conclusion, our study first demonstrated the associations of MET polymorphisms to oral cancer disease susceptibility and clinical statuses." (PMID 39991569, 2025). "In conclusion, these novel findings underscore the role of MET genetic variants in oral cancer susceptibility, particularly in smokers, and highlight the potential of these variants for prognosis and disease prediction." (PMID 39991569, 2025). "The male oral cancer patients who with the genotypic variant “G” of MET rs33917957 were associated with lower risk of cell differentiated grade (p = 0.041)." (PMID 39991569, 2025). "The highest distribution frequencies in oral cancer patients of MET genetic polymorphisms rs41736, rs41739, rs1621, and rs33917957 were polymorphic variant C, polymorphic variant A, polymorphic variant A, and polymorphic variant A, respectively." (PMID 39991569, 2025). "However, the exact expressions of MET/HGF pathway correspond to MET polymorphisms and oral cancer progression and prognosis require future well-designed study to elucidate it." (PMID 39991569, 2025). "In the TCGA database, the MET expressions were upregulated in oral cancer tissues compared to normal tissues, and were correlated with poor cell differentiated and poorer prognoses in smoker groups." (PMID 39991569, 2025). "Several studies including immunotherapeutic strategies and inhibitors of VEGFR, IGF-1R, PI3K/AKT/mTOR and MET have been conducted, being expected in a near future a shift in the management of oral cancer patients towards more personalized treatment." (PMID 27895714, 2016). "Subsequently, the MET oncogene, a tyrosine kinase hepatocyte growth factor (HGF) receptor, was explored in a preclinical (murine model) study, which demonstrated an association between high MET expression levels and oral cancer development." (PMID 34359746, 2021). "Mutations in c-MET are not common in oral cancers (2–13%), but higher MET copy number and increased expression of its ligand, HGF, are frequent." (PMID 35047986, 2020). "As c-Met and EGFR have the same downstream pathways, the activation of MET-HGFR cascade may identify a therapeutic target in oral cancer especially in patients with resistance to EGFR-targeted therapies." (PMID 35047986, 2020).